MMP9 (matrix metallopeptidase 9)
Diseases named in the same sentence as MMP9 in open-access papers (continued):
Sharing a sentence is not in itself a finding about the gene and the disease.
systemic lupus erythematosus (30 papers, 2004 to 2025). An autoimmune multi-organ disease typically associated with vasculopathy and autoantibody production. "MMP9 also plays a pathogenic role in chronic diseases, such as type one diabetes and chronic inflammatory autoimmune diseases, including rheumatoid arthritis, systemic lupus erythematosus, and systemic sclerosis." (PMID 31440381, 2019). "Furthermore, increased MMP9 levels in the sera of patients with systemic lupus erythematosus were shown to be associated with neuropsychiatric characteristics, particularly cognitive dysfunction." (PMID 31440381, 2019). "For instance metalloproteinase-9 (MMP9) is augmented in the sera of systemic lupus erythematosus patients and dipeptidyl peptidase-4/CD26 (DPP4/CD26) in sera of type 1 diabetes, rheumatoid arthritis, systemic lupus erythematosus and inflammatory bowel disease." (PMID 34220840, 2021). "The serum concentrations of these aAb were significantly increased in the LPR−/− lupus mouse model that lacks MMP-9, compared with the single LPR−/− mice." (PMID 30967870, 2019). "NETs from lupus LDGs induced increased accumulation of NET-derived MMP-9 in human umbilical vein endothelial cells (HUVECs) changing their contour, area, perimeter and shape." (PMID 31984378, 2019). "This correlates with a study that demonstrated that at the onset of proteinuria in lupus-prone (NZBxNZW F1) mice there is an increase in proteolytic activity that can be attributed to MMP9 expression." (PMID 31807119, 2019). "Nineteen probes for 16 lupus-relevant genes (Abca1, Apobec3, Ccr7, Ceacam3, Ets1, Foxp3, Hdac1, Ifng, Irf9, Itgam, Jhdm1d, Mmp9, Oscar, Slc4a1, Tbx21, and Tlr7) were identified from the database of male murine spleen." (PMID 30246031, 2018). "Active MMP-9 is externalized on NETs at significantly higher levels in LDGs compared to lupus and control neutrophils." (PMID 25955648, 2015). "Thus, CD138 on lupus T cells is highly sensitive to trypsin cleavage but resistant to MMP9 and collagenases." (PMID 34364875, 2021). "According to a recent review, it concludes a hypothesis for the cognitive dysfunction in systemic lupus erythematosus (SLE): MMP-9 released by prestimulated LDGs can degrade the basal lamina and damage the integrity of BBB." (PMID 34868063, 2021). "Also in NZBxNZW F1 lupus mice, MMP-9 contributed to increase glomerular proteolytic activity around the onset of proteinuria." (PMID 32655553, 2020). "Similarly, D-penicillamine has also been described to induce lupus and is an MMP-9 inhibitor, known to delay experimental autoimmune encephalomyelitis." (PMID 30967870, 2019). "Moreover, genetic knock out of MMP-9 in this lupus mouse model (LPR−/−MMP-9−/−) led to further increases of complement activation in the spleen and kidney." (PMID 30967870, 2019). "Interestingly, significant correlations between MMP-9 and intrathecal levels of neuronal and glial degradation products were noted, indicating ongoing intrathecal degeneration in the brains of lupus patients expressing MMP-9." (PMID 15535833, 2004). "While studying patients with systemic lupus erythematosus (SLE) in patients that were sex- and age-matched with healthy volunteers’ serum levels of MMP-9 and TIMP-1 were determined, the same procedure was performed after CQ treatment." (PMID 34948342, 2021). "Therefore, we selected MMP-9 as renal damage marker representing the degree of proteinuria and the renal infiltrations of myeloid cells that are characteristic of this mice model of lupus." (PMID 32655553, 2020). "In human plasma samples from healthy controls and systemic lupus erythematosus (SLE) patients, we observed a gelatinolytic molecule at 80 kDa, suggestive for activated human MMP‐9." (PMID 30358100, 2019). "Serum levels of MMP-3 in particular have previously been found to correlate with disease activity in RA and MMP-9 in systemic lupus erythematosus (SLE), which is another rheumatic disease." (PMID 26788062, 2015).
systemic lupus erythematosus (continued). "Immunofluorescence microscopy confirmed the presence of MMP-9 and MMP-25 in NETs which indicate that lupus LDGs distinctly upregulate specific MMPs in NETs and are primed for enhanced NETosis." (PMID 31984378, 2019). "Among the patients with systemic lupus erythematosus (SLE), the group of patients in whom at least one neurological or psychiatric symptom, defining NPSLE, occurred, was reported to have increased level of MMP-9 in blood serum." (PMID 28104930, 2016). "Our results suggest that MMP-9 but not MMP-2 actively participates in brain destruction in CNS lupus." (PMID 15535833, 2004). "In addition, immune complexes composed of MMP-9 and anti-MMP-9 in lupus induce NETosis." (PMID 31984378, 2019).
unstable angina (30 papers, 2007 to 2025). "The findings demonstrated a statistically significant association between MMP9 (C1562T) polymorphism and stable angina susceptibility across all genotype model." (PMID 32429880, 2020). "In contrast, one study in 1127 patients with stable and unstable angina showed significant associations between higher MMP-9 levels and cardiovascular mortality with a HR of 2.41 (1.26; 4.60) in the upper quartile." (PMID 28446168, 2017). "MMP-9 C1562G polymorphism may be a risk factor of angina, and is related with ischemic cardiomyopathy and in-stent restenosis." (PMID 26150861, 2015). "In stomach ulcers, curcumin decreased the activity of MMP9, and in patients with angina pectoris, curcumin supplementation reduced the expression of MMP2 and MMP9." (PMID 37237945, 2023). "Serum matrix metalloproteinase 9 (MMP-9) is a candidate biomarker for the early discrimination of MI from unstable angina and a predictor of poor clinical outcomes in patients with ACS." (PMID 36676179, 2023). "Secondary outcome parameters: other circulating inflammatory markers (including IL-6, TNFα, VCAM-1, CD40, sCD40L, MCP-1, and MMP-9), improvement in symptoms of angina and blood stasis syndrome, and safety." (PMID 23983803, 2013). "Whereas few data exist on the association between MMPs during ACS and cardiovascular outcomes, MMP-9 (gelatinase-B) levels are significantly increased in the coronary circulation in patients with acute MI and unstable angina." (PMID 19690647, 2007). "It has been shown that serum MMP-9 could be used to differentiate between MI and unstable angina (UA) with a sensitivity and specificity of 80%." (PMID 36440025, 2022). "Exogenous IL‐10 significantly reduced TNF‐α and MMP9 levels in peripheral blood mononuclear cells of patients with unstable angina, suggesting that a decreased serum level of IL‐10 could be a marker of plaque instability and predict a poor prognosis after an acute ischemic event." (PMID 39801756, 2025). "Secondary outcomes are cTnT, NT-proBNP, inflammatory/endothelial biomarkers (hs-CRP, IL-6, MMP-9, VEGF, HMGB1), and angina-related parameters (attack frequency, symptom severity)." (PMID 41195123, 2025). "They categorized the participants into three groups: the control group, the unstable angina group, and the acute STEMI, overexpression of NEAT1 and MMP-9 was found and they were positively correlated with each other." (PMID 36440025, 2022). "In patients with unstable angina, DSSM can suppress platelet activation and aggregation as well as matrix metallopeptidase 9 (MMP-9) expression and secretion." (PMID 29348768, 2017). "Patients with stable angina had a MMP-9 concentration similar to healthy controls; all patients with UA had elevated levels of MMP-9 at entry, that decreased gradually during hospitalization." (PMID 19578525, 2008). "The expression of MMP-9 is elevated in debris from distal protective vascular guards in patients with ACS but not with stable angina." (PMID 30934954, 2019). "Finally, both MMP-9 and sLOX-1 were able to differentiate patients who had vulnerable plaques from those who did not, among group of patients presenting with unstable angina and ACS, respectively." (PMID 34198543, 2021). "Results showed that administration of curcumin (80 mg/day) to patients with unstable angina was not able to reduce the level of MPO, IL-18 and MMP-9 biomarker." (PMID 31516856, 2019). "In the present study, nanocurcumin administration for 5 days to patients with unstable angina did not affect MPO, IL-18 and MMP-9 levels significantly." (PMID 31516856, 2019). "Results showed that administration of nanocurcumin (80 mg/day for five days) to patients with unstable angina could not reduce the level of MPO, IL-18 and MMP-9." (PMID 31516856, 2019).
metastatic cancer (29 papers, 2010 to 2025). A carcinoma which has spread from the original site of growth to another anatomic site. "Previous studies found that apigenin inhibited the invasion and migration of human metastatic cancer cell lines by reducing MMP-9 expression by suppressing the p38 MAPK signaling pathways." (PMID 34589307, 2021). "Fittingly, acute incubation with the proteases, dispase as well as MMP-9, the latter being a major protease expressed by metastatic cancer cells, led to an enhanced immunofluorescence staining signal upon use of different anti-BSP antibodies." (PMID 34073955, 2021). "MMP-9/NGAL complex was detected more frequently in the urine of metastatic cancer than other types of disease." (PMID 23672427, 2013). "MMP-2 and MMP-9 are the predominant enzymes found overexpressed in metastatic cancers." (PMID 37516013, 2023). "On the other hand, 5-FU (an antimetabolite inhibiting DNA replication) more effectively combated the tumor growth of mCRC, although MMP9 positive metastatic cancer cells remained even after the 5-FU treatment, which was thought to be insensitive, dormant cancer cells in the tumoroids." (PMID 33562088, 2021). "There should be another way around studying the molecular mechanism of how the sample could stop metastatic cancer cell proliferation, instead of MMP9 FRET-based assay being established." (PMID 33800366, 2021). "MMP-9 is reported to be commonly over-expressed in metastatic cancer cells, progenitor cells, local inflammatory infections, acute hypoxia and physical trauma; its expression is regulated by VEGF through the expression of ETS-1 bound to the MMP-9 gene promoter." (PMID 32751717, 2020). "Several studies have indicated that Runx-2 regulates MMP-9 expression in metastatic cancer cells." (PMID 30105080, 2018). "In particular, MMP-2 and MMP-9 were found to be up-regulated in metastatic cancer cell lines." (PMID 28465354, 2017). "This may be due to the expression of hyaluronidases and matrix metalloproteinases, such as MMP-2 and MMP-9, among advanced and metastatic cancers that cleave ECM (including hyaluronic acid) and reduce cell-ECM contacts, adhesion, and the associated intracellular signaling." (PMID 33019572, 2020). "While MMP9 activity performed opposite to MMP3 activity (increased in activity level from the healthy control to pancreatitis, metastatic cancer, and localized pancreatic cancer, respectively), the significant differences between groups tested was similar." (PMID 40292193, 2024). "A previous study revealed FXR as a functional protein in the vasculature of metastatic cancers; moreover, FXR modulated endothelial cell motility via FAK and MMP9 suppression." (PMID 35681743, 2022). "Although more than one MMPs have been identified, MMP-9 is the enzyme most closely correlated with the degradation of ECM and is highly expressed in metastatic cancer." (PMID 28288190, 2017). "Therefore, it is reasonable to hypothesise that expression of MMP-9 could help cancer cells to escape the microenvironmental stresses of nutrient deprivation and that expression of MMP-9 may promote metastatic cancer progression." (PMID 29973599, 2018).
cognitive decline (28 papers, 2015 to 2025). "While higher MMP-9 levels have been shown to correlate with higher levels of AD biomarkers and faster cognitive decline among AD and MCI patients and individuals with genetic risk for AD, sex differences in these associations have not been examined." (PMID 36324151, 2022). "Assessing a potential modulating effect of sex on the association of MMP-9 levels with markers of AD pathology and cognitive decline will help us better understand the factors influencing whether its role in AD is neuroprotective or neurotoxic." (PMID 36324151, 2022). "Resveratrol, popularly presented as ‘the red wine polyphenol’ and sirtuin activator, has been shown in human AD patients, at 2 g/day, to reduce CSF MMP9 levels by approximately one-third as compared to placebo, in association with an attenuation of cognitive decline." (PMID 33921683, 2021). "Moreover, MMP9 expression was increased in the auditory cortex and hippocampus in the age-related hearing loss model, which demonstrated cognitive decline." (PMID 34020590, 2021). "Therefore, the aim of the present study was to determine whether the association between plasma MMP-9 and CSF AD biomarker levels and cognitive decline is modulated by sex in individuals with abnormal levels of Aβ pathology." (PMID 36324151, 2022). "This implies that MMP9 can enhance the neuroinflammation after surgery, contributing to the cognitive decline and MMP9 inhibition promotes the rebalancing of inflammatory factor production." (PMID 40918113, 2025). "Statins have also been reported to have a beneficial effect by reducing hippocampal MMP-9 levels in a rat model of cognitive decline and patients with acute ischemic stroke." (PMID 39403255, 2024). "In AD, high brain levels of MMP9 and CSF MMP9 levels correlated with cognitive decline have been reported." (PMID 38892809, 2024). "Our study’s goal was to examine sex differences in MMP-9 levels and in the association of plasma MMP-9 with CSF AD biomarkers and cognitive decline in individuals on the AD continuum." (PMID 36324151, 2022). "Previous studies have shown that the CypA/MMP9 signaling pathway is responsible for BBB breakdown and subsequent cognitive decline, thus the blockade of CypA/MMP9 signaling can restore BBB integrity and normalize the function of neurons and synapses." (PMID 36337710, 2022). "In this study, plasma MMP9 in different diagnostic groups displayed the following trend: SIVD group > AD group > NC group, and higher plasma MMP9 was correlated with cognitive decline, which was broadly consistent with previous studies." (PMID 36003963, 2022). "We examined the influence of three-week simvastatin (5 mg/kg) administration on hippocampal MMP-9 expression in a rat model of cognitive decline induced by streptozotocin (STZ)." (PMID 30218997, 2019). "Furthermore, an increase in MMP9 was detected in the hippocampus of an animal model of tibial fracture, accompanied by blood-brain barrier disruption and cognitive decline." (PMID 40918113, 2025). "We hypothesized that, in the absence of the regulatory effects of estrogen on MMP-9 activity, older women on the AD continuum would exhibit worse biomarker profiles and faster rates of cognitive decline in relation to higher MMP-9 levels, compared to men." (PMID 36324151, 2022). "Further supporting a pathological role of MMP-9 in AD, pharmacologically inhibiting MMP-9 reversed cognitive decline in AD mice treated with an intracerebral-ventricular injection of a broad-spectrum inhibitor of MMPs and reduced neurodegeneration in β-amyloid-treated cultures." (PMID 32466129, 2020). "Our findings suggest that the modulation of MMP-9 gene expression may be a neuroprotective scheme of simvastatin in battle with the cognitive decline in AD." (PMID 30218997, 2019).
cognitive decline (continued). "With neuroinflammatory changes occurring before the appearance of microhemorrhages, we hypothesize that neuroinflammation induces MMP9 activation leading to microhemorrhages and then cognitive decline." (PMID 31888650, 2019). "The role of MMP9 in age-dependent cognitive decline was also determined." (PMID 28881691, 2017). "We also compared the expression of MMP9 between young and old mouse brains to determine whether MMP9 may contribute to the age-dependent cognitive decline." (PMID 28881691, 2017). "However, the cognitive decline was accompanied with an exacerbated decrease of MMP-9 enzymatic activity and reduction of BDNF mRNA and protein levels in brain, which suggest loss of synaptic plasticity." (PMID 27661129, 2016). "sLRP1 and MMP-9 may be ideal biomarkers of cognitive decline." (PMID 36003963, 2022). "Elevated peripheral MMP9 levels may increase neurodegeneration and cognitive decline." (PMID 36072482, 2022). "MMP9 may also play a role in age-dependent cognitive decline." (PMID 28881691, 2017). "Given that targets such as APOE, MMP9, and CLDN5 are linked to not just vascular pathology but also early-stage cognitive decline and neurovascular disturbance, the discovered ligands could be used to develop early intervention techniques." (PMID 41032496, 2025). "Although MMP-9-induced astrocyte migration plays a role in forming a glial scar and lesion repair, the activated MMP-9 may also disrupt the neurovascular unit by altering synaptic plasticity and leading to cognitive decline." (PMID 38275397, 2024). "Additionally, increased levels of CSF MMP-9 were found in individuals exhibiting low Aβ levels, high tau levels, and APOE ε4 positivity, compared to those with negative biomarkers, indicating a significance of MMP-9 in the early pathophysiology of AD, even preceding cognitive decline." (PMID 38891891, 2024). "Furthermore, the mechanisms by which MMP-9 and TIMP-1 influence neurodegeneration, the reduction in hippocampal volume, and cognitive decline are not yet fully elucidated." (PMID 38891891, 2024).